YTHDF2 (YTH N6-methyladenosine RNA binding protein F2)
Diseases named in the same sentence as YTHDF2 in open-access papers (continued):
Sharing a sentence is not in itself a finding about the gene and the disease.
tumor (continued). "METTL3 (N6-methyladenosine methyltransferase-like 3) enhanced tumor progression via the YTHDF2-dependent inhibition of SOCS2 in HCC." (PMID 39199296, 2024). "The knockdown of YTHDF2 resulted in significant inhibition of sphere formation ability, according to the tumor sphere formation assay." (PMID 38776708, 2024). "Our previous proteomic analysis of five paired HB and normal tissues revealed that YTHDF2 expression is dramatically increased in tumor tissues (Supplementary Excel 3)." (PMID 39247829, 2024). "YTHDF2 is involved in the regulation of Treg cells in the tumor microenvironment (TME), maintaining the survival and function of Treg cells by controlling the TNF-NF-κB signaling pathway within Treg cells." (PMID 39372415, 2024). "IHC staining of subcutaneous tumor tissues revealed that YTHDF2 expression levels were significantly lower in the shYTHDF2 group and significantly higher in the YTHDF2 overexpression group." (PMID 39593172, 2024). "C1q+TAMs specifically express METTL14 and YTHDF2, and maintain the level of tumor infiltration and cytotoxicity of CD8+ T cells in a METTL14-dependent manner." (PMID 39372415, 2024). "YTHDF2 knockdown promotes tumor growth and reduces the sensitivity of anti-PD-1 therapy by enhancing the mRNAs stability of the intrinsic genes PD-1 (PDCD1), CXCR4, and SOX10 in an m6A-dependent fashion." (PMID 36999016, 2023). "The results indicated that HBV infection upregulated MCM2/5 expression through enhanced YTHDF2 O-GlcNAcylation to accelerate tumor formation, whereas OSMI-1 treatment or pSECC-sgYthdf2 exhibited the opposite effect." (PMID 36765030, 2023). "Lastly, a recent report showed that the N6-methyladenosine reader YTHDF2 regulates the anti-tumor functions of TAMs." (PMID 37359522, 2023). "Aberrant YTHDF2 upregulation markedly hampers expression of multiple m6A-marked tumor-suppressing transcripts, including CDKN2B and SPOCK2, and induces oncogenic reprogramming." (PMID 36973285, 2023). "YTHDF2 inhibits tumor cells and the tumor vascular system by regulating interleukin-11 (IL-11) and SERPINE2 mRNAs." (PMID 38072944, 2023). "In xenograft models treated with gemcitabine, the knockdown of YTHDF2 in CFPAC-GM cells resulted in relatively slow tumor growth." (PMID 37605223, 2023). "Our studies conclude that YTHDF2 is capable of regulating neoplastic transformation and cell proliferation among astrocytes by degrading tumor suppressor transcripts including CDKN2B." (PMID 36973285, 2023). "YTHDF2 has also been reported to act as a tumor suppressor in colorectal cancer (CRC), melanoma and osteosarcoma." (PMID 37612540, 2023). "Compared to normal tissues, the mRNA level of YTHDF2 was much lower in tumor tissues, among which 26 cases (26/32, 81.25%) exhibited a decreased expression (less than 0.667-fold change)." (PMID 36870954, 2023). "Mechanistically, METTL3 impedes tumor progression through m6A modification on NF-κB mRNA in a YTHDF2-dependent manner, which in turn attenuates IL-8 production of papillary TC cells to recruit neutrophils, ultimately suppressing tumor progression." (PMID 37915103, 2023). "Increased in GSCs, YTHDF2 plays a vital role in stem maintenance, and it enhances tumour growth in mice through stabilising MYC (YTHDF2-MYC) and targeting IGFBP3." (PMID 36831575, 2023). "Co‐immunoprecipitation (co‐IP) analysis was performed in 11 pairs of tumor or adjacent normal tissues among the samples with higher protein expression of YTHDF2." (PMID 37515378, 2023). "Knockdown of YTHDF2 significantly decreased both tumor volume (P = 0.0304) and tumor weight (P = 0.0496)." (PMID 37012388, 2023). "Immunoblotting showed that YTHDF2 protein levels were markedly higher in HCC tissues than in the corresponding non-tumor tissues (P < 0.001)." (PMID 36765030, 2023). "In the present work, we demonstrated the abnormal expression of YTHDF2 in this type of cancer and its tumor-suppressor roles." (PMID 36870954, 2023).
tumor (continued). "In hypoxia‐induced tumour cells, ubiquitinated YTHDF2 increases its binding to m6A‐modified mRNA to promote mRNA degradation and cancer progression." (PMID 37537731, 2023). "Some researchers have identified the tumour-promoting effect of YTHDF2 by investigating its upstream signaling in PCa." (PMID 37284313, 2023). "The result indicated that YTH family, especially YTHDF1 and YTHDF2, had the potential of asking as a tumor progressing biomarker." (PMID 37833468, 2023). "miR-493–3p and miR-495, tumour suppressor miRNAs in PCa, have been reported to regulate the expression of the YTHDF2." (PMID 37284313, 2023). "This work establishes that increased YTHDF2 hijacks the epitranscriptomic regulatory network by promoting m6A-mediated degradation and silencing of an array of tumor suppressor genes, culminating in neoplastic transformation." (PMID 36973285, 2023). "In gliomas, METTL3 induces the m6A modification and degradation of UBXN2 RNA in concert with YTHDF2, activating the downstream NF-KB signaling pathway and boosting tumor metastasis." (PMID 37996892, 2023). "Correlation analyses of YTHDF1, YTHDF2, and tumor infiltrating lymphocytes (CD4- and CD8-positive T cells and FOP3-positive T regulatory cells (Treg)) were performed on immunohistochemical and gene expression data." (PMID 36479088, 2022). "In a couple of solid tumors, the other group and we have uncovered beneficial roles for regulators, such as METTL3 and YTHDF2, in the immune response to tumor cells by NK cells." (PMID 35296338, 2022). "In brief, METTL3 overexpression in GC promoted the m6A modification of ADAMTS9, a tumor-suppressor gene, and epigenetically prevented its transcription in a YTHDF2-dependent manner." (PMID 35574388, 2022). "Tumor biology studies have shown that YTHDF2 can modulate m6A modification to regulate downstream signaling molecules to regulate tumor cell proliferation, invasion, and migration." (PMID 36035182, 2022). "Correlation analyses among YTHDF1, YTHDF2, and tumor infiltrating lymphocytes were performed using the mRNA expression data of TCGA." (PMID 36479088, 2022). "YTHDF1 has been shown to be involved in tumour cells immune evasion, while YTHDF2 promotes tumour cell proliferation." (PMID 36422864, 2022). "METTL3-catalyzed m6A modifications of the SET domain-containing 7 (SETD7) and kruppel-like factor 7 (KLF7) mRNAs, which function as tumor suppressors, are recognized by YTHDF2 for mRNA decay." (PMID 36226062, 2022). "Growing evidence has shown that YTHDF2 can participate in multifarious bioprocesses, including embryonic development, immune response, and tumor progression." (PMID 35382893, 2022). "As normal samples in the TCGA database are limited, we combined the normal samples from GTEx with the tumor samples from TCGA, and evaluated the expression of YTHDF2 in 27 different cancer types." (PMID 36120577, 2022). "The m6A regulators METTL3, WTAP, FTO and YTHDF2 are elevated in tumor vs control tissues from hepatoblastoma patients and all four regulators contributed to the proliferation and colony formation of HepG2 cells." (PMID 36008936, 2022). "More interestingly, YTHDF2 promoted NK Cell effector function by inhibiting a STAT5-YTHDF2-positive feedback loop involved in tumor progression." (PMID 35186927, 2022). "In Lung Cancer (LC), YTHDF2 expression is increased in tumor tissues, promoted proliferation, and bound to 3′-UTR of 6-phosphogluconate dehydrogenase (G6PD) mRNA." (PMID 35186927, 2022). "YTHDF2 is an N-methyladenosine-binding protein and can modulate mRNA stability, thus impacting central nervous system responses, embryonic development, and tumor evolution." (PMID 36035182, 2022). "Regulation of the m6A reader YTHDF2 by hypoxia involves enhanced inflammation and angiogenesis and thus is critical for tumor invasion." (PMID 35794625, 2022). "It is also found that one of the m6A readers, YTHDF2, accelerates PCa progression by mediating the mRNA degradation of the tumor suppressors." (PMID 35354789, 2022).
tumor (continued). "GSEA confirmed that low YTHDF1 or YTHDF2 tumor expression reflects the gene set of immune hot tumors." (PMID 36479088, 2022). "We studied the differential expression of YTHDF2 in tumor tissues and adjacent normal tissues derived from TCGA database." (PMID 36120577, 2022). "YTHDF2 was dysregulated in various human malignancies and played an oncogenic or tumor-suppressive role by facilitating the degradation of m6A-modified transcripts." (PMID 34759347, 2022). "After tumor purity adjustment, we found that the expression of YTHDF2 was positively correlated with that of majority immune cell marker genes." (PMID 36120577, 2022). "For glycan metabolism, multiple m6A methylation regulators (METTL13/IGF2BP2/YTHDF2, etc.)regulate the development of multiple diseases (e.g., tumor and kidney injury) through glycan metabolism." (PMID 35794625, 2022). "YTHDF2 also promotes tumor proliferation by increasing CDKN1B mRNA degradation in intrahepatic cholangiocarcinoma." (PMID 36479088, 2022). "YTHDF2 was found to be highly expressed in multiple tumor tissues and cells, thereby acting as a carcinogenic factor." (PMID 35382893, 2022). "At last, we analyzed the protein-protein interacting network and related genes of YTHDF2 to enrich its potential functional mechanism in tumor development and progression." (PMID 36120577, 2022). "Depletion of YTHDF2 in NK cells significantly impairs NK cell anti-tumor and antiviral immunity in vivo." (PMID 35254013, 2022). "YTHDF2 was reported to present dual functions in tumors by regulating the proliferation and migration of tumor cells." (PMID 35382893, 2022). "As the disparities exist in different tumor types, the role of YTHDF2 in immune infiltration needs to be further validated." (PMID 36120577, 2022). "Recent studies have confirmed the involvement of YTHDF2 in tumor EMT and its role in regulating tumor cell migration and invasion." (PMID 36017491, 2022). "In mismatch-repair-proficient or microsatellite instability-low (pMMR-MSI-L) CRC and melanoma mouse models, depletion of METTL3 enhances the tumor response to anti-PD-1 treatment through stabilizing the Stat1 and Irf1 mRNA via YTHDF2." (PMID 36008936, 2022). "m6A reader gene YT521-B homology (YTH) domain family protein 2 (YTHDF2) is also upregulated and plays an important role in tumor promotion in AML development/maintenance." (PMID 36035161, 2022). "The corresponding heat map also demonstrated a significant positive correlation between the expression of YTHDF2 and the top five genes in all the tumor types from the TCGA." (PMID 36120577, 2022). "In most cases, the expression of YTHDF2 is upregulated in tumor tissues in comparison with normal tissues, and YTHDF2 plays an oncogenic role in these types of cancers." (PMID 35382893, 2022). "Consistently, IHC analysis revealed that the protein levels of YTHDF2 were also increased compared to the non-tumor controls." (PMID 36566195, 2022). "We also analyzed the correlation between the expression of YTHDF2 and its promoter methylation in various tumor types." (PMID 36120577, 2022). "CCK-8, colony formation and tumor sphere formation assays were performed to illuminate the impact of YTHDF2 to the behavior of UOK109 cells." (PMID 35042525, 2022). "As indicated, the overexpression of YTHDF2 promoted the tumor growth, while TMZ treatment abrogated the effect." (PMID 35582627, 2022). "In order to identify the major cell types that express YTHDF2, we carried out YTHDF2 single-cell analyses using single-cell data from 79 tumor samples." (PMID 36120577, 2022). "Compared to those bearing the vector only, we showed that stable upregulation of YTHDF2 markedly promoted tumor growth in nude mice, as demonstrated by the significant increase in tumor size and weight." (PMID 34996459, 2022). "Altogether, these results show that YTHDF2 downregulation enhances the anti‐tumour effect of cisplatin via both proliferation inhibition and sensitisation of ICC cells to cisplatin treatment." (PMID 35696608, 2022).
tumor (continued). "The results indicated that compared with control cells, AKT and mTOR phosphorylation was significantly increased following YTHDF2 overexpression, which is crucial for tumor progression." (PMID 34996459, 2022). "Low level of circ_0001105 was associated with poor prognosis of OS patients and circ_0001105 overexpression repressed tumor growth by interacting with miR-646 and modulating YTHDF2 expression." (PMID 33817314, 2021). "Most importantly, adding back a shYTHDF2#1-resistant YTHDF2 to the YTHDF2-depleted GSCs rescued the malignant phenotypes of GSCs, suggesting that YTHDF2 is important for GBM tumor growth and invasion." (PMID 33420027, 2021). "The cooperation of METTL3 with the reader protein YTH N6-Methyladenosine RNA Binding Protein 2 (YTHDF2) leads to the degradation of Klf4, which diminishes the tumor suppression activity of Klf4 and consequently induces cancer progression." (PMID 34195082, 2021). "YTHDF2 plays different roles in various cancers, it can promote as well as inhibit tumour progression, playing an important and versatile role." (PMID 34709763, 2021). "For example, YTHDF1 promotes the translation of m6A-marked HINT2 mRNA, a tumor suppressor, which inhibits ocular melanoma progression, and YTHDF2 suppresses cell proliferation and growth via destabilizing the EGFR mRNA in hepatocellular carcinoma." (PMID 33922187, 2021). "A human subcutaneous tumor xenograft model was established to evaluate the role of YTHDF2 attenuation in LUAD tumorigenicity in vivo." (PMID 33980824, 2021). "Here, we found that m6A reader protein YTHDF2 expression was significantly upregulated in EC compare to tumor adjacent tissues, YTHDF2 was then identified to inhibit the proliferation and invasion of EC cell lines." (PMID 34093789, 2021). "Western blotting, quantitative polymerase chain reaction, and immunohistochemistry were used to evaluate the expression levels of YTHDF2 and other molecules in human and mouse tumor tissues and cells." (PMID 34246306, 2021). "In vitro, YTHDF1 and YTHDF2 knockout in cells up-regulated the expression of tumor PD-L1 and changed a variety of immune-related genes." (PMID 35069586, 2021). "In this study, we showed that GSK3β acts as a tumour suppressor gene; m6A‐modifed GSK3β was recognized and degraded by YTHDF2, leading to the activation of Wnt/β‐catenin signalling and further promoting the proliferation of CRC cells in vitro and in vivo." (PMID 34709763, 2021). "As previous study reported, YTHDF2 induced the targeted degradation of the tumor suppressor to accelerate tumor progression, while this regulation was dependent on METTL3‐medicated m6A modification." (PMID 33411363, 2021). "In parallel, it was found that YTHDF2 suppress inflammation and angiogenesis in the tumor cell hypoxia environment." (PMID 34277630, 2021). "In future study, more experiments will be conducted in order to explore the interaction among miR-491-3p, YTHDF2 and Mad2 in tumor suppression in Rb." (PMID 33098307, 2021). "Like the m6A writer proteins METTL3 and METTL14, the m6A reader proteins YTHDF1 and YTHDF2 can act as either an oncogene or a tumor suppressor." (PMID 33922187, 2021). "Compared to the normal tissue, TRMT10C, TRMT6 and YTHDF2 were relatively highly expressed in the tumor tissue, while YTHDC1 was relatively less expressed." (PMID 34777359, 2021). "These two studies indicate tumour-promoting effects of YTHDF2 and dissect the upstream signalling in OC, redefining m6A modification as a signalling hub orchestrating several important pathways, such as the ubiquitin–proteasome system and miRNA." (PMID 34895230, 2021). "It was also proposed that YTHDF2 plays different roles in tumours due to the degradation of its different target mRNAs." (PMID 34246319, 2021). "YTHDF2-knocdown A549 cells grew substantially slower than mock A549 cells, and the average tumor volume and weight of YTHDF2-knocdown A549 cells were markedly smaller compared with mock A549 cells." (PMID 33980824, 2021).